HAND2 (heart and neural crest derivatives expressed 2)
Diseases named in the same sentence as HAND2 in open-access papers (continued):
Sharing a sentence is not in itself a finding about the gene and the disease.
pancreatic carcinoma (1 paper, 2019). "In BxPC3 pancreatic carcinoma cells Aurora kinase-A mediated phosphorylation of TW at S123, T148 and S184 promote increased malignant phenotypes and inhibit TW heterodimerization with E12 and Hand2." (PMID 31540485, 2019).
paraganglioma (1 paper, 2025). A benign or malignant neoplasm arising from paraganglia located along the sympathetic or parasympathetic nerves. "Both paraganglioma and panNETs with paraganglioma-like morphology show S100-positive sustentacular cells complicating the differential diagnosis, which is mainly based on the lack of low weight cytokeratins positivity and GATA3, tyrosine hydroxylase, PHOX2B, and Hand2 expression in the former." (PMID 40668487, 2025).
pleural mesothelioma (1 paper, 2022). A neoplasm that arises from the mesothelial cells of the pleura. "Analyzing expression levels of HAND2 using qPCR in human pleural mesothelioma (MPM) (n = 36) compared to healthy pleura (n = 4), we observed that individual tumors showed heterogeneous yet consistent upregulation of HAND2, with individual tumors expressing high levels of HAND2 mRNA (p = 0.0596)." (PMID 35354817, 2022).
rectal cancer (1 paper, 2018). A primary or metastatic malignant neoplasm that affects the rectum. "Recent studies revealed that HAND2 was significantly hypermethylated and downregulated in colon and rectal cancer." (PMID 30237858, 2018).
renal hypoplasia (1 paper, 2016). Renal hypoplasia is a developmental anomaly in which one or both kidneys (unilateral or bilateral renal hypoplasia, respectively) have a deficit in the number of nephrons and may be small. "In this regard, it is interesting to note that there are case reports of chromosomal duplications containing HAND2 in patients with renal hypoplasia." (PMID 27805568, 2016).
tumor (23 papers, 2009 to 2025). "To assess the relative importance of HAND2 methylation in human endometrial carcinogenesis, we tested for any associations between HAND2 methylation and well-known molecular characteristics of the tumours." (PMID 24265601, 2013). "It has been indicated that gradual age-associated epigenetic silencing of HAND2 in the endometrial stroma could inactivate the progesterone tumor suppressor pathway, sensitizing endometrial epithelial cells to oncogenic oestrogen, thus predisposing them to carcinogenic transformation." (PMID 30482885, 2018). "MAGI2 hypermethylation disrupts Wnt/β‐catenin signaling, promoting tumor invasiveness, while HAND2 hypermethylation impairs progesterone signaling, contributing to hormone therapy resistance." (PMID 40528483, 2025). "HAND2 is one tumor suppressor by targeting ERK signaling and one potential epigenetic driver gene in CRC." (PMID 35870943, 2022). "We also performed studies in vivo on tumor growth and xenograft formation in constructed stable cell lines to assess the suppressor role of HAND2 in CRC." (PMID 35870943, 2022). "In a Chinese cohort of CRC patients, HAND2 methylation was greatly increased in CRC tissue than paired normal tissues (tumor: 2.73% ± 3.43%; normal: 0.31% ± 0.40%; n = 74 pairs, P < 0.001) by qMSP." (PMID 35870943, 2022). "The downstream classic MAPK/ERK signaling of HAND2 is clarified and HAND2 acts as a tumor suppressor in CRC." (PMID 35870943, 2022). "From the CRC network, only ASCL1 emerged from this analysis, given its different dynamic expression during murine TH-MYCN-driven tumor formation compared to HAND2, PHOX2B, GATA3 and ISL1." (PMID 34638267, 2021). "Of these, heart and neural crest derivatives expressed 2 genes (HAND2 and SALL1) reported to be hypermethylated and associated with tumorigenesis in tumor tissues." (PMID 30237858, 2018). "Collectively, it is suggested that HAND2 has characteristics of tumor suppressor genes in several types of tumors." (PMID 30237858, 2018). "We undertook this by analysing the expression of NA markers that we characterised in Xenopus AVNA development (Ascl1, Hand2, Phox2a and TH) in NB primary tumours, using publicly available microarray data." (PMID 25786414, 2015). "Specifically HAND2 mediates the tumour suppressive effects of progesterone." (PMID 25692570, 2015). "In this study we found the combination of scoring for HAND2, PTEN, and PAX2 was able to align staining patterns with diagnosis of EIN or HwA based on diagnostic criteria and might be useful in identifying those most likely to have benign disease." (PMID 36303676, 2022). "Although various genes such as ADCYAP1, HAND2, MME, and RASSF1A have been reported to exhibit abnormal methylation and tumor development in UCEC, the role of CCND2 gene methylation in UCEC has not been reported." (PMID 40678058, 2025). "Tumor cells were characterized by high expression of NB tumor signature genes (PHOX2B, HAND2, STMN2, and KCNQ2), which were exclusively expressed in the BM of metastatic patients with NB." (PMID 38358826, 2024). "HAND2 reconstitution can inhibit cell proliferation, invasion and migration in vitro, and also suppress CRC growth in tumor xenograft." (PMID 35870943, 2022). "In contrast, the tumor size and weight were dramatically reduced by ART treatment than the control group, while the effect was significantly abolished when knockdown HAND2 expression." (PMID 33511117, 2020). "Notably, miR-181b-5p and miR-877-5p acted as negative regulators of tumor-suppressor genes (e.g., HEY2, MCL2, HAND2), while miR-204-5p and miR-143-3p appeared to indirectly target oncogenes (e.g., RAB10, DR1, PTBP3, NCBP1)." (PMID 41009685, 2025). "As expected, we observed HAND2 could directly bind to ERK both in DLD1 cells and HCT8 cells, which indicated HAND2 reconstitution could bind to ERK and reduce its phosphorylation for ERK inactivation to inhibit tumor growth." (PMID 35870943, 2022).
tumor (continued). "In this study, we found HAND2 reconstitution could bind to ERK and reduce its phosphorylation for ERK inactivation to inhibit tumor growth." (PMID 35870943, 2022). "Remarkably, Hand2, Phox2b, Gata3 and Isl1 were highly expressed in both TH-MYCN+/+ early hyperplasia and wild-type ganglia at week 1 and remained at this level in both tissues throughout further tumor development." (PMID 34638267, 2021). "Finally, TBX2 expression is positively correlated with GATA3, HAND2, and PHOX2B expression levels as well as with those of other potential CRC genes important in development in a NB tumor cohort (n = 283)." (PMID 30451831, 2018). "We found that NB primary tumours have high expression of PHOX2A, HAND2 and TH." (PMID 25786414, 2015).
cancer (15 papers, 2013 to 2025). A tumor composed of atypical neoplastic, often pleomorphic cells that invade other tissues. "HAND2 may be a contributing factor to cancer risk and serve as a prognosis biomarker for endometrial cancer." (PMID 26949191, 2016). "In support of this hypothesis, the researchers report that HAND2 methylation was increased in premalignant endometrial lesions (cancer-prone, abnormal-looking tissue) compared to normal endometrium, and was associated with suppression of HAND2 expression." (PMID 24265601, 2013). "But the underling mechanism and cellular functions of HAND2 in cancer are unknown." (PMID 35870943, 2022). "High‐frequency cancer‐specific methylation and silenced expression of HAND2, as well as low survival rate, were demonstrated in CRC." (PMID 39957375, 2025). "In other cancers, HAND2 acts as a TS, downregulated in numerous cancer types, including NSCLC, ovarian, breast, gastric, colorectal, cervical, endometrial, prostate, and esophageal squamous cell cancer." (PMID 38110859, 2023). "High frequency of HAND2 cancer-specific methylation and silenced expression and poor survival are shown in CRC." (PMID 35870943, 2022). "These roles of HAND2 methylation indicates HAND2 is a potential cancer-specific driver gene in early carcinogenesis, not only a passive epigenetic event." (PMID 35870943, 2022). "Cancer and organismal injuries were the top two diseases and function categories that were predicted to increase, along with neurological (HAND2), hepatic system (APOE, CACNG4, CAMK2B), respiratory system (WNT16), and skeletal muscle developmental disorders (ADD2, HAND2)." (PMID 39508990, 2025). "Recent evidence has suggested that HAND2 methylation is a common and crucial molecular alteration in several types of cancers, and could be employed as a potential biomarker for the early detection as well as a predictor of the treatment response." (PMID 28959347, 2017). "Several transcription factors, including PPARγ, C/EBP, Nrf2, HOX, and HAND2, are involved in BPA action on fat and liver homeostasis, the cardiovascular system, and cancer." (PMID 32796699, 2020). "HAND2 was expressed at higher levels in MSC lines than in iPSCs and cancer cell lines." (PMID 39621192, 2025). "We analyzed a group of genes that were upregulated in MSC lines compared to cancer cell lines, including transcription factors (ZBTB16, HAND2, and TWIST1), a cadherin regulating cell adhesion (CDH20), a receptor tyrosine kinase (PDGFR-α), and a negative cell cycle regulator (CDKN2A)." (PMID 39621192, 2025). "Firstly, epigenetic alterations, such as HAND2 methylation, are important functional event during early tumorigenesis and not just cancer passive characteristics." (PMID 35870943, 2022). "The expression of HAND2 (heart- and neural crest derivatives-expressed 2) and TWIST1 (twist family bHLH transcription factor 1) was significantly upregulated, while the expression of NKX2-5 (NK2 Homeobox 5) was significantly downregulated in MSCs compared to cancer cell lines." (PMID 39621192, 2025). "However, little is known about the role of HAND2 in CRC and other cancer types." (PMID 35870943, 2022). "The transcription factor HAND2, which was selected in both breast (BRCA), colon (COAD), and lung (LUAD) cancers, is enriched in breast fibroblasts but not necessarily enriched in either cancer type." (PMID 40453216, 2025).
heart disease (1 paper, 2021). "Although the Hand 2 transcription factor is a widely known regulator of cardiac development, studies have also shown that Hand2 plays a role in heart disease in postnatal mice." (PMID 33942477, 2021).
HAND2 also shares sentences with these, for which no sentence is quoted: pulmonary stenosis (3 papers); double outlet right ventricle (2); alveolar rhabdomyosarcoma (1); aortic stenosis (1); atrial septal defect (1); atrial tachycardia (1); auriculocondylar syndrome (1); breast carcinoma (1); cardiovascular diseases (1); carotid atherosclerosis (1); Cirrhosis (1); cleft palate (1); diabetic cardiomyopathy (1); dilated cardiomyopathy (1); disorders of pregnancy (1); Endometrial Intraepithelial Neoplasia (1); esophageal cancer (1); Ewing sarcoma (1); fibrosis (1); folic acid deficiency (1); Fuhrmann syndrome (1); Hyperglycemia (1); Hypertension (1); hypertrophic cardiomyopathy (1); Inguinal hernia (1); kidney cancer (1); lymphedema (1); of pregnancy (1); Phocomelia (1); preeclampsia (1).
A further 5 diseases each share a sentence with HAND2 in 1 paper.